CASC2 (cancer susceptibility 2)
Diseases named in the same sentence as CASC2 in open-access papers (continued):
Sharing a sentence is not in itself a finding about the gene and the disease.
tumor (continued). "In addition, most lncRNAs are up-regulated to sponge microRNAs and promote cancer development and progression, while, some of them are down-regulated and act as tumor suppressors; these include lncRNAs STXBP5-AS1, TUSC8, PTENP1, and CASC2." (PMID 34703793, 2021). "In this study, CASC2 expression was significantly decreased in CRC tissues and CRC cell lines, and decreased expression was significantly more frequent in patients with advanced tumor-node-metastasis stage disease (TNM III and IV) (P = 0.028)." (PMID 27198161, 2016). "Further investigation indicated that CASC2, as a tumor suppressor lncRNA, could directly regulate PIAS3 expression by acting as a ceRNA for miR-18a, leading to STAT3 inactivation and inhibiting in vitro and in vivo CRC tumor growth." (PMID 38185635, 2024). "Finally, 5 lncRNAs (CASC2, AL078459.1, AL390066.1, STK4-AS1 and HOXA-AS3) yielded statistical significance (p < 0.05) in multivariate logistic analysis with age at diagnosis and tumor pathology stage as covariates." (PMID 31470869, 2019). "The results showed that CASC2 knockdown promoted the cell viability while TRAIL treatment suppressed the cell viability of HepG2R and Rel-7402R cell; the suppressive effect of TRAIL on tumor cell viability could be partially reversed by CASC2 knockdown." (PMID 29476051, 2018). "Combined with the results from luciferase assays, CASC2 competitively binds to miR-24/miR-221 to reduce binding of miR-24/miR-221 to downstream caspase 3/8, thereby affecting TRAIL-resistant tumor cell viability, caspase 3/8 protein levels, and finally TRAIL-induced tumor cell apoptosis." (PMID 29476051, 2018).
cancer (51 papers, 2015 to 2026). A tumor composed of atypical neoplastic, often pleomorphic cells that invade other tissues. "In clinical practise, low levels of CASC2 are associated with a more aggressive cancer phenotype and shorter survival time." (PMID 38790894, 2024). "CASC2 (cancer susceptibility candidate) is another lncRNA candidate for the diagnosis of GBM, with its downregulation also reported in endometrial, lung, gastric, colorectal, and bladder cancer." (PMID 38790894, 2024). "Implicated in other cancers like endometrial and colorectal, CASC2 normally appears to function as a tumor suppressor." (PMID 33920158, 2021). "It has been reported that miR-93-5p and long non-coding RNA (lncRNA) Cancer Susceptibility 2 (CASC2) play opposite roles in regulating chondrocyte apoptosis, indicating the possible interaction between them." (PMID 31931772, 2020). "Cancer susceptibility candidate 2c (CASC2c) is one of three lncRNA transcripts produced by the alternative splicing of cancer susceptibility 2 (CASC2)." (PMID 33299889, 2020). "LncRNA cancer susceptibility candidate 2 (CASC2), located on chromosome 10q26, plays a regulatory role as an anti-cancer factor in various cancers, such as hepatocellular carcinoma and pancreatic carcinoma." (PMID 32774472, 2020). "Several lncRNAs have been identified as prognostic factors in cancers, such as metastasis-associated lung adenocarcinoma transcript 1 (MAlAT1) and cancer susceptibility 2 (CASC2)." (PMID 31227613, 2019). "Long noncoding RNAs cancer susceptibility candidate 2 (CASC2) have been demonstrated as playing crucial regulatory roles in a few of cancers." (PMID 28199978, 2017). "In addition, cancer susceptibility 2 (CASC2) and cancer susceptibility 19 (CASC19) have been demonstrated to exhibit proinflammatory and proapoptotic effects by regulating IL-17 and the miR-152-3p/DDX6 axis, respectively." (PMID 37189327, 2023). "The next lncRNA identified in this work is CASC2 (cancer susceptibility 2)." (PMID 36294833, 2022). "Although the dysregulated expression of CASC2 in cancer patients highlights its tumorigenic properties, the molecular mechanisms underlying CASC2-mediated tumorigenesis remain largely unknown." (PMID 27198161, 2016). "CASC2, cancer susceptibility candidate 2, has been associated with endometrial cancer." (PMID 26284813, 2015). "CASC2 is also revealed in other cancers, such as gastric, colorectal, and endometrial, always with reduced expression." (PMID 36294833, 2022). "Upregulation of lncRNA CASC2 inhibited the cancer cells viability and elevated the apoptosis in cancer cells." (PMID 36685962, 2022). "Restoring CASC2 levels by transfecting cultured 786-O and A498 RCC cell lines with a vector encoding CASC2 prevented abnormal cancer cell growth, proliferation, and migration." (PMID 33920158, 2021). "LncRNA CASC2 (hereafter called CASC2) has been extensively investigated in a range of cancers where it regulates proliferation, migration, invasion, metastasis, and angiogenesis through different mechanisms." (PMID 34440661, 2021). "CASC2 participate in cancer biology mainly by regulating cancer cell behaviors, such as inhibiting cell proliferation and promoting cell apoptosis." (PMID 31931772, 2020). "The down-regulation of lncRNA CASC2 participates in the regulation of multiple cellular behaviors of cancer cells, such as proliferation and apoptosis." (PMID 31015370, 2019). "Among these orthologs, the human ortholog is known as CASC2, and is suppressed in lung, colorectal, renal, and other cancers by miR-21-5p targeting via the conserved 7-mer site." (PMID 30103450, 2018). "CASC2 is known to play an oncogenic role in OSCC as well as in other malignant tumors." (PMID 36497491, 2022). "It was found that by inhibiting miR-221, CASC2 could mediate the sensitivity of cancer cells to apoptosis induced by anti-cancer agent TRAIL and upregulated Caspase-3, which is a direct target of miR-221." (PMID 33414456, 2021).
cancer (continued). "CASC2 is an anticancer lncRNA that is downregulated in many cancers, including colorectal cancer." (PMID 33805687, 2021). "Previous studies indicated that CASC2 could serve as a competing endogenous RNA (ceRNA) or miRNA sponge in the development of cancers." (PMID 33134385, 2020). "Moreover, the patients were divided into high (n = 21) or low (n = 25) CASC2 level group according to its mean abundance in cancer tissues." (PMID 33134385, 2020). "Given that PH and cancer were shared with some common features, like excessive cellular proliferation and apoptosis resistance, we were interested to unveil whether lncRNA CASC2 is involved in PH pathogenesis." (PMID 30857524, 2019). "Therefore, we selected SOCS1 which was involved in cancer cell proliferation, migration, invasion and drug resistance, as a potential CASC2 target." (PMID 31728180, 2019). "Long non-coding RNAs (lncRNA) CASC2 is a key player in cancer biology." (PMID 31015370, 2019). "LncRNA CASC2 has been well studied in the development of different types of human cancers." (PMID 31015370, 2019). "CASC2, a recently discovered lncRNA, has been demonstrated to play roles in several human cancers." (PMID 31134151, 2019). "The lncRNA CASC2 was demonstrated to be dysregulated in numerous cancers." (PMID 30675129, 2019). "LncRNA CASC2 is down-regulated during the development of cancers." (PMID 31015370, 2019). "Therefore, it is reasonable to speculate that lncRNA CASC2 affects the response of cancer cells to TRAIL through two different modes of action." (PMID 35145900, 2021). "It has also been reported that downregulation of lncRNA CASC2 mediated by E2F6 predicts worse outcomes and facilitates cancer progression in GC patients." (PMID 34532281, 2021). "The biofunction “development of carcinoma” was one of the top cancer-related enriched biofunctions (p-value of 0.0176), with 8 DE lncRNAs: PVT1, CASC2, PCA3, EPB41L4A-AS1, C10orf25, CYTOR, FOXD2-AS1, and CRNDE." (PMID 33926464, 2021). "For example, baicalin, berberine, curcumin, and EGCG induce cell cycle arrest and apoptosis and decrease the proliferation of cancer cells by overexpression of NKLA, PAX8-AS1, CASC-2, NBR2, XIST, NEAT-1, SOX2OT-V7, respectively." (PMID 33805687, 2021). "We detected that lncRNA CASC2 expression was comparatively lower in T24 and 5637 cell lines than that in SW780, J82 and UMUC3 cancer cell lines." (PMID 28199978, 2017). "To explore the role of CASC2 in PTC, we first measured its expression in 46 cancer tissues." (PMID 33134385, 2020). "Taken together, these observations suggest CASC2 as a ceRNA plays an important role in CRC pathogenesis and may serve as a potential target for cancer diagnosis and treatment." (PMID 27198161, 2016). "Furthermore, CASC2 inhibits miR-21 and p-AKT protein level and promotes PTEN protein level, indicating that CASC2 might sensitize cancer cells to drugs through regulating PTEN and Akt pathways." (PMID 34975466, 2021). "In contrast, CASC2 v.1 and v.3 were downregulated by TGF-β in A549 and MDA-MB-231 cells, while the expression of DSCAM-AS1 and SOX2-OT was not affected significantly by TGF-β activation in these cancer cells." (PMID 41556346, 2026).
adenocarcinoma (1 paper, 2023). A common cancer characterized by the presence of malignant glandular cells. "miR-4735-3p has previously been described to target mammalian target of rapamycin (mTOR)-dependent signaling, by interacting with the long non-coding (lnc) RNA Cancer Susceptibility 2 (CASC2) that plays an important role in inhibiting proliferation and migration of adenocarcinoma cells." (PMID 38162033, 2023).
CASC2 also shares sentences with these, for which no sentence is quoted: acute kidney injury (3 papers); prostate carcinoma (2); acute pancreatitis (1); Diabetic Foot Ulcers (1); esophageal carcinoma (1); gallbladder cancer (1); gastrointestinal tumors (1); head and neck cancer (1); infection (1); kidney damage (1); lung carcinoma (1); mental disorder (1); nasopharyngeal carcinoma (1); nodular goiter (1); ovarian cancer (1); renal failure (1); status epilepticus (1); viral infections (1).